ZNF789 (zinc finger protein 789)
Description:
May be involved in transcriptional regulation.
Tractability: No criterion of Open Targets' tractability assessment is met for any kind of drug.
Gene: Protein-coding gene on chromosome 7 (99,472,832 to 99,503,650, forward strand). Ensembl gene ENSG00000198556.
Subcellular location: Nucleus
Subcellular location (Human Protein Atlas): Nucleoplasm
Gene Ontology:
Molecular function: protein binding; DNA-binding transcription factor activity, RNA polymerase II-specific; RNA polymerase II cis-regulatory region sequence-specific DNA binding
Biological process: regulation of transcription by RNA polymerase II; regulation of DNA-templated transcription
Cellular component: nucleoplasm; nucleus
Genetic constraint (gnomAD): Loss-of-function variants: 11 observed, 16.99 expected, observed/expected ratio (o/e) 0.65, 90% interval 0.41 to 1.07. The upper end of that interval is the gene's LOEUF score, 1.07, which puts it in group 4 of 6, group 1 being the genes least tolerant of losing a copy. Missense variants: 461 observed, 541.16 expected, observed/expected ratio (o/e) 0.85, 90% interval 0.79 to 0.92. Synonymous variants: 159 observed, 186.17 expected, observed/expected ratio (o/e) 0.85, 90% interval 0.75 to 0.97.
Homologues: Orthologues: chimpanzee ZNF789 (99% identical), macaque ZNF789 (95% identical), dog ZNF789 (73% identical), pig ZNF789 (63% identical). Paralogues in human: ZNF658 (38% identical), ZNF484 (37% identical), ZNF568 (37% identical), ZNF605 (37% identical), ZNF234 (37% identical), ZNF30 (37% identical), ZNF7 (37% identical), ZNF227 (37% identical), ZNF41 (37% identical), ZNF879 (37% identical), ZNF175 (36% identical), ZNF182 (36% identical), and 164 more.
Diseases named in the same sentence as ZNF789 in open-access papers:
ZNF789 is named in the same sentence as 4 diseases in open-access papers, as found by Europe PMC text mining. Sharing a sentence is not in itself a finding about the gene and the disease. The quoted sentences say what the papers report.
endometriosis (2 papers, 2022 to 2025). The growth of functional endometrial tissue in anatomic sites outside the uterine body. "The correlation of testosterone levels in patients with endometriosis with polymorphisms rs148982377 ZNF789 and rs34670419 ZKSCAN5 was shown." (PMID 41373783, 2025). "Endometriosis-involved epistatic interactions were found between eight loci of sex hormone genes (without rs148982377 ZNF789) within twelve genetic simulation models." (PMID 36430184, 2022).
breast carcinoma (1 paper, 2019). "For breast cancer, the number of KRAB‐ZNF‐positive samples was slightly different: (ZNF205 – 6/11, ZNF320 – 10/10, ZNF485 – 11/11, ZNF643 – 11/11, ZNF695 – 12/12, ZNF 707 – 10/10, and ZNF789 – 2/12)." (PMID 30444046, 2019). "Finally, these factors (ZNF273, ZNF485, ZNF695, ZNF643, and ZNF789), together with ZNF714, had significantly increased mRNA levels in the DNA methylation cluster 5 identified for breast cancer, which also coincides with the basal‐like subtype and the lowest overall DNA methylation level." (PMID 30444046, 2019).
tumor (1 paper, 2019). "Within these 148 comparisons, significantly higher expression in normal tissues compared to tumor tissues was observed only in six cases (ZNF138 in KIRC and THCA, ZNF200 in THCA, ZNF273 in PRAD, ZNF485 in THCA, and ZNF789 in KICH)." (PMID 30444046, 2019).
ZNF789 also shares sentences with these, for which no sentence is quoted: cancer (3 papers).